TACSTD2 (tumor associated calcium signal transducer 2)
Description:
May function as a growth factor receptor.
Synonyms: GA733-1; M1S1; TROP2; EGP-1; EGP1; GA7331; GP50
Tractability: Antibody: UniProt predicts a signal peptide or a membrane-spanning region; its Gene Ontology location is reachable by antibodies, with medium confidence; the Human Protein Atlas places it where antibodies can reach. PROTAC: ubiquitination databases record sites on it. Other modalities: an approved drug acts on it.
Gene: Protein-coding gene on chromosome 1 (58,575,433 to 58,577,252, reverse strand). Ensembl gene ENSG00000184292.
Subcellular location: Membrane
Subcellular location (Human Protein Atlas): Plasma membrane; Nucleoli; Vesicles
Gene Ontology:
Molecular function: protein binding
Biological process: negative regulation of branching involved in ureteric bud morphogenesis; negative regulation of cell motility; negative regulation of epithelial cell migration; negative regulation of ruffle assembly; negative regulation of stress fiber assembly; negative regulation of substrate adhesion-dependent cell spreading; positive regulation of stem cell differentiation; visual perception; regulation of epithelial cell proliferation; ureteric bud morphogenesis
Cellular component: extracellular exosome; plasma membrane; basal plasma membrane; cytosol; lateral plasma membrane; membrane; nucleus; extracellular region
Genetic constraint (gnomAD): Loss-of-function variants: 13 observed, 9.93 expected, observed/expected ratio (o/e) 1.31, 90% interval 0.84 to 1.87. That is too few expected variants to judge how well the gene tolerates losing a copy. Missense variants: 511 observed, 423.13 expected, observed/expected ratio (o/e) 1.21, 90% interval 1.12 to 1.3. Synonymous variants: 220 observed, 194.07 expected, observed/expected ratio (o/e) 1.13, 90% interval 1.01 to 1.27.
Homologues: Orthologues: chimpanzee TACSTD2 (100% identical), pig TACSTD2 (85% identical), rabbit TACSTD2 (84% identical), dog TACSTD2 (80% identical), rat Tacstd2 (80% identical), mouse Tacstd2 (79% identical), tropical clawed frog epcam (45% identical), zebrafish epcam (33% identical). Paralogues in human: EPCAM (48% identical).
Diseases named in the same sentence as TACSTD2 in open-access papers:
TACSTD2 is named in the same sentence as 218 diseases in open-access papers, as found by Europe PMC text mining. Sharing a sentence is not in itself a finding about the gene and the disease. The quoted sentences say what the papers report.
breast cancer (165 papers, 2011 to 2026). A primary or metastatic malignant neoplasm involving the breast. "The TACSTD2 gene encodes the Trop-2 protein, and its high expression is correlated with a poor prognosis in breast cancer." (PMID 38352694, 2023). "According to the GEPIA database, TACSTD2 was highly expressed in various solid tumours, including OC, breast cancer, and bladder cancer." (PMID 41331197, 2025). "Patients with breast cancer with TACSTD2-high tumors also experienced significantly worse OS following immune checkpoint inhibitors." (PMID 38986529, 2024). "TACSTD2 is an E2 regulated gene that is a prognostic indicator for endometrial cancer disease-free survival, is overexpressed in some breast cancers, and exhibits an Early Up trajectory." (PMID 38663407, 2024). "While TACSTD2 has shown therapeutic progress in breast cancer 34, 35, our single-cell transcriptome analysis revealed its limited feasibility for treating ovarian cancer." (PMID 38817863, 2024). "Upon examination of copy number alterations (CNAs), only breast cancer demonstrated a significant pattern of differential prevalence based on TACSTD2 expression." (PMID 38986529, 2024). "The results indicated that the TACSTD2 gene is expressed across all breast cancer subtypes, with a particularly wide expression range in luminal A and TNBC subtypes." (PMID 39555080, 2024). "They screened for correlation between TACSTD2 gene expression and the expression of selected genes involved in the development of breast cancer." (PMID 39555080, 2024). "We first assessed expression of genes highly correlated with TACSTD2 expression in breast tumors and corresponding patient-derived xenografts (PDXs) and found that 29 genes were overlapping between in 18 breast cancer samples and matching PDXs." (PMID 37567892, 2023). "Expression of TACSTD2 was then compared to expression of CDH1 in breast cancer cell lines from The Cancer Cell Line Encyclopedia (CCLE) (N = 51) and The Library of Integrated Network-Based Cellular Signatures (LINCS) (N = 35)." (PMID 37567892, 2023). "Previous publications indicate that multiple RTKs families have been found in various cancers, for instance, VEGFR-2 in BC and TACSTD2 in breast cancer, non-small-cell lung cancer, and thyroid cancer." (PMID 36297654, 2022). "Trophoblastic cell surface antigen-2 (Trop-2, also known as EGP-1, encoded by TACSTD2) is a transmembrane glycoprotein overexpressed in 83% of breast cancer cases and 85% of TNBCs." (PMID 36209184, 2022). "Another study reported that the upregulation of TACSTD2 regulates breast cancer invasiveness and subsequently, correlates with poor prognosis." (PMID 31164716, 2020). "EpCAM positive circulating breast cancer cells were enriched for TACSTD2 expression linking it to a higher metastatic capability of tumor cells." (PMID 31772156, 2019). "Our finding that TROP2 is silenced by promoter methylation in the Tamoxifen-resistant breast cancer cell line prompted us to manipulate TACSTD2 expression in cell lines." (PMID 30002602, 2018). "The other type of gene switch shows predominantly one modality in the breast cancer samples, and is where we discover the TACSTD2 (Trop2) gene." (PMID 22053771, 2011). "Our experimental studies on multiple breast cancer cell lines confirm the switch-like behavior of TACSTD2 and provide evidences for the transcriptional regulation of the gene." (PMID 22053771, 2011). "In light of these studies, our analysis uncovered TACSTD2 gene to have a switch-like behavior, with CREB as a possible regulator, which is activated in breast cancer and modulates the transcription of TACSTD2." (PMID 22053771, 2011). "We characterized the TACSTD2 gene, and found it to be distinctively expressed at higher levels in almost all of the breast cancer samples, ER+/-, HER2+/- subtypes." (PMID 22053771, 2011).
breast cancer (continued). "Recent studies, along with our analysis of breast cancer samples, found TACSTD2 to be highly expressed in a variety of epithelial cancers and show low to no expression in normal somatic cells." (PMID 22053771, 2011). "Experiment shows that TACSTD2 expression is high in breast cancer cell lines, MCF-7 and MDA-MB-231, and FI treatment enhances the expression of TACSTD2." (PMID 22053771, 2011). "Our mining approach uncovered a unique expression pattern of TACSTD2 in breast cancer, and experiments confirmed TACSTD2 show bimodal behavior in breast cancer cell lines." (PMID 22053771, 2011). "We confirm that the expression of TACSTD2 gene is high in breast cancer cell lines MCF7 and MDA-MB-231 as compared with non-cancer cells (i.e. primary rat astrocyte)." (PMID 22053771, 2011). "We observe a significant increase in the correlation between the expression level of CREB and TACSTD2 in the breast cancer samples." (PMID 22053771, 2011). "Moreover, while TACSTD2-high tumors appeared to exhibit a more immune “hot” microenvironment, patients with breast cancer with TACSTD2-high tumors experienced a worse response to ICI." (PMID 38986529, 2024). "In TACSTD2-low breast cancer, FGFR inhibition may also merit further consideration, due to enrichment of FGF/R fusions." (PMID 38986529, 2024). "Knocking down TACSTD2 expression (the Trop-2) in breast cancer MCF7 cells increased proliferation." (PMID 38203255, 2023). "MCF7 cells are recognized as EsR+ and TACSTD2+ breast cancer cells." (PMID 36133203, 2019). "Experimental confirmation of the computational results suggest TACSTD2 could be a potential biomarker and attractive candidate for drug therapy against both ER+ and ER- subtypes of breast cancer, including the triple negative subtype." (PMID 22053771, 2011). "Combining computational prediction and experimental analysis, we found that CREB could regulate TACSTD2 in breast cancer cells, and suggest a potential feedback structure of TACSTD2 regulation." (PMID 22053771, 2011). "In our analysis we also found TACSTD2 to be highly expressed in many colon cancer samples and shows bimodality, however the percentage of colon cancer samples with TACSTD2 at the ON state (~60%) are less than in breast cancer (~99%), suggesting TACSTD2 could be a better target for breast cancer." (PMID 22053771, 2011). "It consists of a humanized IgG1κ monoclonal antibody targeting TROP2 (TACSTD2), a glycoprotein overexpressed in 80% of poor prognosis breast cancers, coupled to the topoisomerase I inhibitor SN-38 through a hydrolyzable linker." (PMID 38506114, 2024). "It ranks the importance of hub-gene in ARG subgroups identification, and the top3 genes are SFN, TJP3 and TACSTD2, amongst while only TJP3 (HR = 1.95, p = 1.3e-8) is prognosis-related gene in breast cancer." (PMID 37950731, 2023). "Similar to TACSTD2, the same study also suggested that hsa-miR-489-5p, an onco-miR, is a direct target of GSE1 and exhibits suppressed expression in breast cancer cells." (PMID 34439112, 2021). "Overall, our computational analysis demonstrate a distinctively high expression of TACSTD2 in almost all ER+/-, HER2+/- subtypes of breast cancer." (PMID 22053771, 2011). "After establishing that TROP2 protein expression was present in almost all non-metaplastic breast cancer, but in very few metaplastic breast tumors, we then sought to compare TACSTD2 gene expression in breast tumors sequenced in The Cancer Genome Atlas (TCGA)." (PMID 37567892, 2023). "Studies of tamoxifen-resistant breast cancer cells found these cells develop altered activation of CREB and AP-1, which we speculate could be related to TACSTD2 signaling." (PMID 22053771, 2011). "The expression of TACSTD2 is turned OFF in most normal samples but ON in almost all of the breast cancer samples independent of the subtypes." (PMID 22053771, 2011).
triple-negative breast carcinoma (81 papers, 2014 to 2026). An invasive breast carcinoma which is negative for expression of estrogen receptor (ER), progesterone receptor (PR), and human epidermal growth factor receptor 2 (HER2). "Furthermore, antibody-drug conjugates targeting Trop2 (TACSTD2), such as Sacituzumab govitecan, have shown therapeutic effects in triple-negative breast cancer 14, indicating that TACSTD2 is a promising therapeutic target." (PMID 38817863, 2024). "Tacstd2 expression was positively correlated with EMT scores in both our mouse tumor scRNA-seq dataset and human triple-negative breast cancer (TNBC) samples from the TCGA-BRCA cohort, based on bulk RNA-seq data." (PMID 41280107, 2025).
prostate carcinoma (61 papers, 2009 to 2026). A carcinoma that arises from epithelial cells of the prostate gland. "Interestingly, TACSTD2 is highly expressed in prostate cancer and is associated with the severity and prognosis of the tumor." (PMID 38698420, 2024). "Similarly, our study shows that in lymph-node-positive breast cancer and prostate cancer patients, low expression of TACSTD2 mRNA associates with worse prognosis." (PMID 33187148, 2020). "TACSTD2 is upregulated in prostate cancer cells and can be secreted into sEVs to affect receptor cell function." (PMID 38698420, 2024). "Senescent luminal cells highly express tumor-associated calcium signal transducer 2 (TACSTD2) and are associated with prostate cancer." (PMID 38698420, 2024). "TACSTD2 was unmethylated in prostatic intraepithelial neoplasia and hypermethylated/down-regulated in 17% of prostate cancers." (PMID 37456256, 2023). "Recent studies have shown that TACSTD2 has a critical role in the metastasis of prostate cancers by modulating β1 integrin function, and activation of PAK4 induced by TACSTD2 was observed in the experiment." (PMID 25202389, 2014). "The CK19+CK8+Clu+Tacstd2+Sca1+ luminal epithelial progenitor cells as identified in this study are strong candidate tumor initiating cells in the Pten knockout prostate cancer model." (PMID 19461893, 2009). "This hypothesis is supported by findings that TACSTD2 promotes cell motility in prostate cancer cells by modulating the ß1 integrin signaling and increases wound healing by promoting stem cell survival." (PMID 31772156, 2019). "Interestingly, despite this implication of TACSTD2 in pluripotency and contemporary knowledge that TACSTD2high basal cells efficiently form spheres in vitro, the role of TACSTD2 in prostate cancerization and therapy response is under-explored or, rather, unclear." (PMID 34439112, 2021). "In prostate cancer, GSE1 is frequently upregulated, whereas TACSTD2 exhibits downregulation; this inverse correlation promotes metastatic dissemination, castration resistance, and disease progression, while also modulating clinical and immune parameters in patients." (PMID 41208974, 2025).
pancreatic cancer (53 papers, 2008 to 2025). "Both the CPA4 and TACSTD2 proteins are overexpressed in pancreatic carcinoma in humans and are associated with decreased survival." (PMID 35169238, 2022). "In CRC, both KRAS-wildtype (wt) and KRAS-mutant (mt) groups with TACSTD2-high tumors experienced worse OS, while in pancreatic cancer, this was observed only in patients with KRAS-mt tumors." (PMID 38986529, 2024). "Most notably, neutrophils were significantly elevated in TACSTD2-high breast, colorectal, pancreatic, and urothelial cancer, and M1 macrophages were elevated in TACSTD2-high breast, colorectal, liver, and pancreatic cancer." (PMID 38986529, 2024). "Patients with TACSTD2-high breast, CRC, and pancreatic cancers demonstrated a significantly shorter OS than TACSTD2-low tumors." (PMID 38986529, 2024). "FGFR3 and ARID1A mutations may represent actionable targets in TACSTD2-high urothelial cancer, while KRAS mutations may be an attractive target for TACSTD2-high CRC and pancreatic cancer." (PMID 38986529, 2024). "While the increase in TACSTD2 levels in metastatic tissue was small, this difference could nonetheless contribute to the worse survival observed among patients with breast, colorectal, and pancreatic cancer with TACSTD2-high tumors." (PMID 38986529, 2024). "Among all pathogenic KRAS mutations, the prevalence of G12C was similar between TACSTD2-high versus TACSTD2-low groups in both CRC (7.3% vs 6.4%) and pancreatic cancer (1.5% vs 1.5%; P > .05; data not shown)." (PMID 38986529, 2024).
lung carcinoma (52 papers, 2009 to 2026). "We also revealed that the diagnostic value of TACSTD2 for tumors was significantly greater than that of CEA, which is consistent with previous lung cancer studies." (PMID 38698420, 2024). "They further showed that promoter methylation is correlated with decreased TACSTD2 expression in lung cancer cell lines and tumors." (PMID 30002602, 2018). "Lin and colleagues reported that knockdown of TACSTD2 in lung cancer cells expressing high levels of endogenous TACSTD2, increased AKT activation and promoted growth." (PMID 30002602, 2018). "Tacstd2 is a potential tumor suppressor gene in lung cancer development." (PMID 26000093, 2015). "Other genes that we chose (e.g., CD24, TACSTD1, TACSTD2, CEACAM1, and PRKCD) are correlated with lung carcinoma or other tumors." (PMID 19874631, 2009). "The co-expression of EGFR and MUC1 was higher in tumor cells than EGFR combined with targets under active drug development for lung cancer such as MET, HER3 (ERBB3) or Trop2 (TACSTD2), suggesting the potential safety advantage of developing therapies targeting EGFR and MUC1." (PMID 39664199, 2024).
ovarian carcinoma (49 papers, 2012 to 2026). A malignant neoplasm originating from the surface ovarian epithelium. "Although TACSTD2 has been reported to be associated with metastasis and a poor prognosis marker in ovarian cancer 15, its relevance to platinum resistance and the underlying mechanism have not been discovered." (PMID 38817863, 2024). "TROP2, a trophoblast cell-surface antigen, also known as tumor-associated calcium signal transductor (TACSTD2) is overexpressed in a variety of human epithelial cancers, including breast, lung, gastric, colorectal, pancreatic, prostatic, cervical, head-and-neck, and ovarian carcinomas." (PMID 36620535, 2022). "TACSTD2, which can be detected in ovarian cancer-derived exosomes, plays an important role in the invasion, migration and glycolysis in ovarian cancer." (PMID 41331197, 2025). "Further analysis of GEO sequencing data for ovarian cancers revealed higher TACSTD2 expression in resistant cells than in sensitive cells (p<0.001)." (PMID 38817863, 2024). "RNA-seq analysis revealed that TACSTD2 primarily enhances the biological functions of ovarian cancer cells through the PI3K-AKT, MAPK, Calcium, Rap1 signalling pathways." (PMID 38817863, 2024). "Bulk RNA-seq investigating TACSTD2 expression across various cancer indicated significantly elevated expression in ovarian cancer (Tumour=376, Normal=180, p<0.001)." (PMID 38817863, 2024). "The results underscored a positive relationship, revealing that higher TACSTD2 expression in ovarian cancer tissues was associated with elevated IC50 values for cisplatin, suggesting TACSTD2 as a predictor of cisplatin treatment response." (PMID 38817863, 2024). "The findings of this study provide a theoretical basis for the combination of TACSTD2 antibodies with cisplatin, in the treatment of ovarian cancer." (PMID 38817863, 2024). "We also revealed that TACSTD2, a representative gene of the E0 subcluster, was a resistance gene that mediated platinum resistance in ovarian cancer through the Rap1/PI3K/AKT pathway." (PMID 38817863, 2024). "Herein, we demonstrated that elevated TACSTD2 expression leads to cisplatin resistance in ovarian cancer cells through the Rap1/PI3K/AKT signalling pathway." (PMID 38817863, 2024). "Although TACSTD2 promotes the malignant progression of various cancers, including ovarian cancer, no studies have reported that TACSTD2 causes cisplatin resistance in ovarian cancer." (PMID 38817863, 2024). "Our combined analysis and experimental results suggested that TACSTD2 regulates the PI3K/AKT pathway through the Rap1 signalling pathway in ovarian cancer cells, thereby modulating AKT phosphorylation and influencing the cytotoxicity of platinum-based treatment in ovarian cancer cells." (PMID 38817863, 2024). "Survival analysis further corroborated these findings, demonstrating that heightened TACSTD2 expression was linked to poor overall survival (OS) and progression-free survival (PFS) in patients treated with platinum-based therapy and in all ovarian cancer patients." (PMID 38817863, 2024). "Therefore, investigating TACSTD2 can not only enhance understanding of the pathogenesis of ovarian cancer but also reveal new therapeutic strategies, particularly for patients who have developed resistance to conventional chemotherapy." (PMID 38817863, 2024). "Therefore, exploring the expression and mechanism of TACSTD2 provides valuable insights for future ovarian cancer treatments." (PMID 38817863, 2024). "Furthermore, we have discovered that TACSTD2 may promote the progression of ovarian cancer by regulating glycolysis." (PMID 41331197, 2025). "TACSTD2 (tumour-associated calcium signal transducer 2), also known as Trop2 (trophoblast antigen 2) or GA7331 (gastrointestinal tumour-associated antigen), is a cell surface glycoprotein that has been implicated in cancer metastasis and as a poor prognosis marker 10-13, including ovarian cancer." (PMID 38817863, 2024).
ovarian carcinoma (continued). "Based on this analysis, we found that TACSTD2 modulates the PI3K/AKT pathway through the Rap1 signalling pathway, thereby influencing AKT phosphorylation, and subsequently influencing ovarian cancer cell sensitivity to platinum-based treatment." (PMID 38817863, 2024).